PRCD (photoreceptor disc component)
Description:
Involved in vision.
Synonyms: RP36
Tractability: Antibody: its Gene Ontology location is reachable by antibodies, with high confidence.
Gene: Protein-coding gene on chromosome 17 (76,527,586 to 76,553,578, forward strand). Ensembl gene ENSG00000214140.
Subcellular location: Cell projection, cilium, photoreceptor outer segment; Membrane; Endoplasmic reticulum; Golgi apparatus
Gene Ontology:
Molecular function: opsin binding
Biological process: detection of light stimulus involved in visual perception
Cellular component: cytoplasm; endoplasmic reticulum; extracellular region; Golgi apparatus; membrane; photoreceptor outer segment membrane; photoreceptor outer segment
Genetic constraint (gnomAD): Loss-of-function variants: 12 observed, 9.65 expected, observed/expected ratio (o/e) 1.24, 90% interval 0.79 to 1.84. That is too few expected variants to judge how well the gene tolerates losing a copy. Missense variants: 61 observed, 70.71 expected, observed/expected ratio (o/e) 0.86, 90% interval 0.7 to 1.07. Synonymous variants: 31 observed, 25.75 expected, observed/expected ratio (o/e) 1.2, 90% interval 0.9 to 1.62.
Homologues: Orthologues: chimpanzee PRCD (98% identical), macaque PRCD (98% identical), rabbit PRCD (85% identical), dog PRCD (80% identical), guinea pig PRCD (80% identical), pig PRCD (76% identical), mouse Prcd (72% identical), rat Prcd (69% identical).
Diseases named in the same sentence as PRCD in open-access papers:
PRCD is named in the same sentence as 10 diseases in open-access papers, as found by Europe PMC text mining. Sharing a sentence is not in itself a finding about the gene and the disease. The quoted sentences say what the papers report.
retinitis pigmentosa (4 papers, 2013 to 2022). Retinitis pigmentosa (RP) is an inherited retinal dystrophy leading to progressive loss of the photoreceptors and retinal pigment epithelium and resulting in blindness usually after several decades. "The patient with retinitis pigmentosa discloses a homozygous mutation of PRCD-R17C with the RP phenotype." (PMID 36142714, 2022). "Several mutations in PRCD are linked to retinitis pigmentosa (RP) in canines and humans, and while recent studies have established that PRCD is required for high fidelity disc morphogenesis, its precise role in this process remains a mystery." (PMID 33087780, 2020). "However, in retinitis pigmentosa is not a common feature, and therefore, it is remarkable that nearly all patients with PRCD mutations reported in the literature carry this phenotypic characteristic." (PMID 23805042, 2013).
retinal dystrophies (3 papers, 2019 to 2023). "Lapponian herders (LHs) are affected with several types of inherited retinal dystrophies, and variants in PRCD and BEST1 genes have been associated with generalized PRA and canine multifocal retinopathy 3 (cmr3), respectively." (PMID 33606121, 2021). "A third genetic form of inherited retinopathy is suspected in LH, as not all cases of inherited retinal dystrophies have been explained by the known PRCD and BEST1 variants." (PMID 33606121, 2021).
retinal degeneration (2 papers, 2020). Degeneration of the retina. "This fact was established over a decade ago, with the identification of PRCD mutations as the cause for retinal degeneration in dogs and humans." (PMID 33213002, 2020).
retinal diseases (2 papers, 2007 to 2023). "We compared the significantly dysregulated genes identified in this screen (FDR <0.05) against genes linked to inherited retinal diseases and identified 5 genes: RGR, PRCD, CDH3, GM2A, and CYP2U1." (PMID 37115691, 2023).
PRCD also shares sentences with these, for which no sentence is quoted: Cone rod dystrophy (2 papers); autosomal recessive congenital ichthyosis 10 (1); autosomal recessive retinitis pigmentosa (1); diabetes (1); neuronal ceroid lipofuscinosis 4 A (1); Stargardt disease (1).